CD44 (CD44 molecule (IN blood group))
Diseases named in the same sentence as CD44 in open-access papers (continued):
Sharing a sentence is not in itself a finding about the gene and the disease.
hepatocellular carcinoma (163 papers, 2009 to 2026). A malignant tumor that arises from hepatocytes. "The expression of CD44 and its isoforms has also been associated with a poor prognosis in liver carcinomas." (PMID 41168417, 2025). "CD44s, the standard variant of CD44, and CD44v, representing different variant isoforms of CD44, are expressed in liver carcinoma." (PMID 41168417, 2025). "PCBP1 (alpha CP1 or hnRNPE1) has been characterized as a negative regulator of CD44 variants splicing in the human hepatoma cell line HepG2." (PMID 38106992, 2023). "A CD44-incorporated Hepatocellular Carcinoma Risk Index Scoring Tool (CHRIST) was formulated utilizing clinical and genetic variables." (PMID 35200757, 2022). "Moreover, OPN and CD44 are highly expressed in hepatocellular carcinoma CSCs and are associated with increased incidence of tumour relapse and unfavourable prognosis." (PMID 34944493, 2021). "Overexpression of CD44 is associated with low expression of E-cadherin, high expression of vimentin, a high percentage of phospho-Smad2 positive nuclei and poor prognosis in hepatocellular carcinoma (HCC) patients." (PMID 26985909, 2016). "In the present study, we provide convincing evidence that human PCBP1 regulates CD44 alternative splicing in human hepatoma cell line HepG2 cells, and loss of PCBP1 in human hepatic tumor may contribute to the formation of a metastatic phenotype." (PMID 20361869, 2010). "In a murine model, whole body CD44 knockout resulted in reduced induction of liver carcinomas following DEN-induced carcinogenic liver injury." (PMID 41168417, 2025). "In hepatocellular carcinoma, the expression of TGF‐β is associated with partial EMT augments, mesenchymal genes, CD44 and CD133, and it maintains the activation of epithelial‐related genes." (PMID 41346572, 2025). "Conversely, maintaining optimal cholesterol levels can inhibit HCC development by activating NK cells to target hepatoma cells and facilitating the translocation of CD44 into lipid rafts." (PMID 40270603, 2025). "In hepatocellular carcinoma, its downregulation leads to a poor prognosis and early recurrence, correlating negatively with cancer stem cell markers (i.e., CD44, CD133)." (PMID 39202425, 2024). "In hepatocellular carcinoma, two patients with both xCT and CD44 expression had moderate or intense accumulation of 18F-FSPG, whereas two patients with negative CD44 expression showed mild 18F-FSPG retention." (PMID 38067277, 2023). "For example, in vivo injection of TAMs promoted the expression of the hepatocellular carcinoma (HCC) stem cell annotator CD44 in mice, which was consistent with the results of the coculture of TAMs and CSCs in vitro (the proliferation of CSCs was promoted)." (PMID 35733919, 2022). "As the in vivo results demonstrated that CD44 is overexpressed in hepatocellular carcinoma, the next step was to evaluate the expression of this receptor in human liver cancer cell lines." (PMID 35164326, 2022). "RAB14 recycling by CHML was shown to enhance cellular migration and invasion through improved trafficking of regulators of metastasis such as Mucin 13 and CD44 to the cell membrane in hepatocellular cancer." (PMID 36471277, 2022). "CD44 has been demonstrated to play a pivotal role in regulating tumor cell progression, including hepatocellular carcinoma (HCC) development." (PMID 35200757, 2022).
hepatocellular carcinoma (continued). "Since CD44+/CD133+ cells account for an important subpopulation of hepatic CSCs, immunofluorescent analysis further confirmed that LECT2 therapy significantly decreased the CD44+/CD133+ hepatic CSCs in Novikoff hepatoma (∗∗p < 0.01)." (PMID 36055405, 2022). "The antitumour activity of CD44-CAR T cells was also investigated for hepatocellular carcinoma in vitro and in vivo." (PMID 34944493, 2021). "In contrast, a positive relationship has been found between CD44 and miR-221, both of which are upregulated in hepatocellular carcinoma cells and tumours." (PMID 34944493, 2021). "CD44-CAR T cells had stronger tumour growth suppression capacity and prolonged survival in CD44+ hepatocellular carcinoma xenograft mice compared to normal and mock T cells." (PMID 34944493, 2021). "IC-2, a novel small-molecule Wnt inhibitor, can reduce the population of CD44+ (liver CSCs) and the sphere-forming ability of hepatocellular carcinoma (HCC) cells." (PMID 32456660, 2020). "Debanjan Dhar’s work has thrown light upon the pivotal role of CD44 in the tumorigenesis of hepatocellular carcinoma." (PMID 33303029, 2020). "In line with this, the STAT3/IL-6 pathway was reported to be involved in the increased frequency of CD44+ hepatocellular carcinoma (HCC) stem cells, when co-cultured with TAMs isolated from HCC-bearing patients." (PMID 32397392, 2020). "CD44 has also been reported to be a direct target of nicotinamide N-methyltransferase (NNMT) in hepatocellular carcinoma." (PMID 33303029, 2020). "The prominent role of CD44 in escaping anoikis was further strengthened by a study linking the CD44-expressing subsets of two hepatocellular carcinoma cell lines to anoikis resistance." (PMID 32984308, 2020). "In a recent study, Mansoori and coworkers (2020) tested the ability of hyaluronic acid-modified 5-fluorouracil (5-FU) -loaded, nanosized liposomes against colorectal cell lines (CD44-expressing) and a hepatoma cell line (non-CD44 expressing)." (PMID 32580366, 2020). "In hepatocellular carcinoma (HCC), tumor-associated macrophages promote CD44+ stem-like cell expansion, and IL-6/STAT3 signaling inhibition using Tocilizumab (TCZ) inhibits this expansion." (PMID 30804456, 2019). "Hepatocellular carcinoma tissues collected at Tottori University Hospital were used to determine the mRNA expression levels of CD44, NOTCH3, and GPX1." (PMID 30636370, 2019). "In hepatocellular carcinoma, the underlying molecular mechanism by which AZGP1 inhibits cell migration and invasion is regulating the PTEN/Akt and CD44 pathways." (PMID 31632499, 2019). "Nevertheless, combined therapy remained most potent in depleting the CD44/CD133 expression in rat hepatoma." (PMID 29683262, 2018). "We have shown that the micelles were highly stable in vitro and selectively deliver more loads to HepG2 cell which is hepatocellular carcinoma cell line previously reported to express high levels of CD44." (PMID 28127555, 2017). "OPN also increased the tumorigenicity of cancers such as hepatocellular carcinoma in a CD44-dependent manner." (PMID 29254164, 2017). "Similar reports are available where anti-CD44 antibodies conjugated with liposomal nanoparticles carrying doxorubicin drug molecules can selectively target CD44+ CSCs in hepatocellular carcinomas and limiting the side effects of conventional chemotherapy." (PMID 28785557, 2017). "Consistent with previous studies, we have found that CD133 (+) hepatocellular cancer cells highly express stemness genes (CD44, EpCAM, Oct4 and KLF4) and exhibit increased sphere formation capacity compared to the CD133 (−) cells." (PMID 26506419, 2015). "Immunohistochemical analysis showed that the immunostaining of CD133 and CD44 was significantly reduced in celecoxib-treated hepatoma compared with that in control." (PMID 24721996, 2014).
hepatocellular carcinoma (continued). "This was consistent with the results of immunoblot analysis, which showed a significantly decreased CD133 and CD44 protein levels in celecoxib-treated hepatoma tissues." (PMID 24721996, 2014). "Histological analysis revealed that celecoxib therapy reduced the abundance of CD44 + /CD133 + hCSCs in hepatoma tissues." (PMID 24721996, 2014). "We also found Ad-PTEN gene delivery suppressed hCSCs marker expression and tumor initiating, and PTEN knockdown up-regulated CD133 and CD44 in hepatoma cells." (PMID 24721996, 2014). "Previously studies have shown that CD44 expression in hepatoma and cervical cancer cells was regulated via NF-κB binding in the promoter of CD44 gene." (PMID 25184276, 2014). "We first examined COX-2 expression and the spatial distribution of CD44+/CD133+ hCSCs in Novikoff hepatoma using immunohistochemical and immunofluorescent analyses, respectively." (PMID 24721996, 2014). "In hepatocellular carcinomas, CD44 antisense oligonucleotide significantly down-regulated CD44 expression, induced apoptosis, decreased tumorigenesis and invasion, and increased the cancer cell sensitivity to chemotherapy drugs." (PMID 21541039, 2011). "For instance, CD44+ hepatocellular carcinoma xenografts treated with CD44-CAR T cells demonstrated a significant decrease in tumor volume in comparison with mock T and normal T cells; CD44 tumor volumes were unchanged in comparison with CD44-CAR T, mock T and normal T cells." (PMID 40114966, 2025). "Recent findings showed that elevated cholesterol levels promote the lipid raft localization of CD44 in a palmitoylation-dependent manner, disrupting CD44-Ezrin interactions, and ultimately decreasing the migration and metastasis of hepatocellular carcinoma (HCC) cells." (PMID 40681504, 2025). "However, the evidence pointing to CD44 accumulation in bladder and hepatic carcinoma cells following proteasome inhibitor MG132 treatment indicates a potential role for proteasomes in CD44 protein degradation." (PMID 40806710, 2025). "In turn, a clinical study of patients with hepatocellular carcinoma showed that increased expression of the CD44 marker in the perioperative period may predict early relapse after radical surgery." (PMID 39020106, 2024). "Hepatitis C virus infection has been shown to elevate CD44 expression in hepatocellular carcinoma." (PMID 39148690, 2024). "Cholesterol synthesis was significantly correlated with metastasis of hepatocellular carcinoma by attenuating CD44-Ezrin binding, which could inhibit cell migration." (PMID 37568802, 2023). "TAMs activated STAT3 to produce IL-6 and induced an increase in the number of CD44+ hepatoma cells." (PMID 35740975, 2022). "Likewise, immunohistochemical analysis showed that intratumoral LECT2 gene delivery significantly inhibited the expression of CD133 and CD44 in Novikoff hepatoma tissues." (PMID 36055405, 2022). "Targeting the CD44 expressed in hepatocellular carcinoma in metastatic hepatocellular CSCs using anti-CD44 antibody-coated exosomes could directly induce CSC death." (PMID 34062950, 2021). "In this study, we examined the clinical implications of the variables, TIPRL, LC3, CD133, and CD44, all of which have been reported on in terms of their roles in liver cancers and autophagy, including hepatocellular carcinomas (HCCs) and intrahepatic cholangiocarcinomas (iCCA)." (PMID 34208132, 2021). "Similarly, crosstalk between the TGF-β pathway and CD44 expression upregulation was observed in oral and oesophageal cancer and hepatocellular carcinoma." (PMID 34944493, 2021). "In hepatocellular carcinoma, miR-199a-3p suppresses cancer cell proliferation by targeting CD44." (PMID 31718630, 2019). "This study aimed to determine whether CD44 polymorphisms were correlated with hepatocellular carcinoma (HCC) and to reveal a new potential target for early prediction, prevention, and diagnosis of HCC." (PMID 31301090, 2019).
hepatocellular carcinoma (continued). "Overexpression of c-Fos promotes cell invasion and migration via the CD44 pathway in oral squamous cell carcinoma, and may contribute to the metastasis and cell migration of human hepatocellular carcinoma." (PMID 27602752, 2016). "Metabolically, palmitate supplied by FASN inhibits hepatocellular carcinoma (HCC) metastasis through CD44 lipid raft sequestration." (PMID 40626019, 2025). "CD44+ hepatocellular carcinoma (HCC) PDOs is significantly resistant to sorafenib, and sorafenib increases Hedgehog signaling protein and CD44 levels." (PMID 37693042, 2023). "CD44 is one of the critical markers of hepatocellular carcinoma (HCC) among the cancer stem cells (CSCs)." (PMID 33062675, 2020). "IC-2, a novel small-molecule Wnt inhibitor, reduced the population of CD44+ cells (liver CSCs) and the sphere-forming ability of hepatocellular carcinoma (HCC) cells, as well as in CRC and bladder cancer cells." (PMID 33276800, 2020). "TGF-β1 was also reported to promote the invasive property of CD44-positive hepatocellular carcinoma (HCC) by inducing mesenchymal transformation." (PMID 32585841, 2020). "Recent evidence demonstrates that exogenous CS enhanced hepatoma sphere formation by blocking specific protein binding to CD44, while the addition of exogenous heparin inhibited sphere formation, indicating that heparin and its derivatives are potential candidates for reducing hepatoma stem cells." (PMID 32538273, 2020). "In addition to the regulation of cancer progression, such as ovarian cancer cells, TAM-secreted IL-6 is also reported to increase the expansion of CD44+ stem cells as well as sphere formation of the hepatocellular carcinoma cells, thus promoting tumor progression through cancer stem cell growth." (PMID 32283687, 2020). "CD44 expression positively correlates to the expression of YAP in hepatocellular carcinoma (HCC) and high expression of CD44 or YAP correlates to worse pathology grade, increased vascular invasion and more severe liver cirrhosis." (PMID 30935014, 2019). "CD44 has been reported to be involved with tumor growth and metastasis and has also been implicated as a CSC marker in hepatocellular carcinoma (HCC)." (PMID 27330410, 2016). "We then evaluated whether celecoxib affected the abundance of CD44+/CD133+ hCSCs in hepatoma cells." (PMID 24721996, 2014). "Preclinical inhibition of CD44 using monoclonal antibodies or gene silencing has reduced tumor cell proliferation, MDSC recruitment, and fibrotic signaling in hepatocellular carcinoma." (PMID 41155434, 2025). "In the case of hepatocellular cancer, exosomal protein biomarkers include CTLA-4, which activates the PTEN/CD44 signal pathway, and LOXL4, activating the FAK/Src pathway." (PMID 41502528, 2025). "In hepatocellular carcinoma (HCC), type I collagen promotes cancer cell stemness and metastasis through the CD44/DDR1/YAP axis and the PSD4/ARF6 signaling pathway, respectively." (PMID 40563472, 2025). "Knockdown of CD44 in HLE cells, a cell line generated from hepatocellular carcinoma, sensitized them to sorafenib in a TGFβ-dependent manner." (PMID 41168417, 2025). "CD44-positive hepatocellular carcinoma (HCC) patient-derived organoids (PDOs) exhibit significant resistance to sorafenib, and sorafenib increases CD44 levels." (PMID 39919692, 2025). "In patients with grade 1 intrahepatic carcinomas and grade 1 hepatocellular carcinomas (HCCs), TIPRL/LC3/CD133/CD44 also play a key role in prognosis." (PMID 38783892, 2024). "CD44-CAR T cells were more effective in suppressing tumor growth and increasing survival in CD44+ hepatocellular carcinoma mice." (PMID 38672650, 2024). "In a study of hepatocellular carcinoma, it was found that the cancer stem cell marker molecules CD133 and CD44 were distributed mainly at the edge of hepatocellular carcinoma stem cell colonies." (PMID 38041196, 2023).
hepatocellular carcinoma (continued). "The expression of XDH inversely correlates with the expression of cancer stem cell–related genes, such as CD44 or CD133, and their downregulation promotes TGFβ signaling in hepatocellular carcinoma." (PMID 37239828, 2023). "In hepatocellular carcinoma (HCC), CD44 also induces a mesenchymal phenotype by activating TGFβ pathway, consequently promoting cancer migration and metastasis." (PMID 38455361, 2023). "In both in vitro and in vivo studies, in hepatocellular carcinoma (HCC), the cancer stem cell-like CD133+/CD44+ cells with high OPN levels were more sensitive to DNA methylation inhibitor, 5 Azacytidine (5 Aza)." (PMID 36672705, 2023). "By flow cytometry analysis for hepatic CD44+/CD133+ CSCs, rLECT2 treatment dose-dependently and significantly deprived CD44+/CD133+ subpopulation in hepatoma cells." (PMID 36055405, 2022). "In addition, expression of CD44 in hepatocellular carcinoma (HCC) promotes sorafenib resistance and tumorigenicity." (PMID 34831048, 2021). "Treating human hepatocellular carcinoma cells with tocilizumab, a humanized anti-IL-6 receptor antibody, or knockdown of STAT3 in these cells attenuated the growth of CD44+ cancer stem cells that were induced by TAMs." (PMID 32283687, 2020). "Through changing the histone H3 methylation on 27 methylation pattern and activating CD44 at transcriptional level, NNMT displays significantly promotes vascular invasion and distant metastasis of hepatocellular carcinoma." (PMID 33303029, 2020). "A recent study has shown that 4-MU treatment significantly reduced expression of CD44, CD133, CD90 and EpCAM in hepatic carcinoma cells in vitro." (PMID 31443261, 2019). "In hepatocellular carcinoma (HCC), CD133+/CD44+ cells are one subgroup with high stemness and responsible for metastatic relapse and resistance to treatment." (PMID 30064482, 2018). "PTEN gene delivery by adenovirus reduced CD44/CD133 expression in vitro and hepatoma formation in vivo." (PMID 24721996, 2014). "The rhOPN-induced CXCR4 expression is dependent on CD44 and integrin receptors, and is regulated by the PI-3K/Akt and JNK pathways in the two hepatocellular carcinoma cell lines (HepG2 and SMMC7721) tested." (PMID 21909361, 2011). "To confirm the inhibition of CD44 v6 expression by PCBP1, we performed the assays in another hepatocellular carcinoma cell line SMMC-7721 cells and the similar results were obtained." (PMID 20361869, 2010). "In addition, STRAP knockout in hepatocellular carcinoma decreased mRNA abundance of stemness markers and liver progenitor genes, including AXIN2, LGR5, CD133, and CD44." (PMID 34206917, 2021). "Fusion of hepatoma (HepG2) cells and embryonic stem cells (ESCs) produces more tumorigenic fusion cells, which are similar to TSCs, with enhanced expression of the TSC markers CD133, ALDH1 and CD44." (PMID 32632040, 2020). "In concordance with a previous study in hepatocellular carcinoma, we found that KLF5 inhibition dramatically decreased the spheroid growth and downregulated the expression of stem cell markers such as CD44, CD133, NANOG and OCT4 in EOC cells." (PMID 33424607, 2020). "On the contrary, chemotherapy reduced CD44 and CD133 expression in this rat orthotopic hepatoma." (PMID 29683262, 2018). "Recent reports have identified CTSCs, which have CSC-like potential and enhanced metastatic capacity in various solid tumors, such as breast, colon, and hepatocellular carcinoma, using a combination of EpCAM and CSC markers in the each tumor (e.g., CD44 or CD133)." (PMID 26897248, 2016). "However, miR-199a-3p is frequently downregulated in hepatocellular carcinoma, where it targets PAK4, CD44, and mTOR [14, 15, and 16] and displays antiproliferative/tumor suppressor functions." (PMID 25839163, 2015).